CCL2 (C-C motif chemokine ligand 2)
Diseases named in the same sentence as CCL2 in open-access papers (continued):
Sharing a sentence is not in itself a finding about the gene and the disease.
tumor (continued). "Considering that the experimental setup in this study lacks the components of a tumor microenvironment, the reduction in PDGF-BB, CCL2, and VEGF could be due to the absence of endothelium-exposing signals." (PMID 38543085, 2024). "Nevertheless, ectopic expression of cSERPINE2 in MCF-7 cells did not regulate the expression of EIF4A3 or CCL2 or activation of the JAK2-STAT3 pathway, which indirectly indicated that cSERPINE2 overexpression did not affect tumor cell proliferative and invasive capacity in vitro." (PMID 36797769, 2023). "Thus, while CCL2 blockade may not exert a cytotoxic effect on tumor cells, anti-CCL2 agents may abrogate tumor cell migration and block the cycle of tumor cell recruitment to sites of metastasis—allowing for cytotoxic therapies to obtain control of the tumor cell population." (PMID 37964011, 2023). "TNC dominated the behavior of tumor-resident myeloid cells; CCL2 did not impact macrophage survival/activation whilst TNC facilitated an immune suppressive macrophage phenotype that was not dependent on or altered by CCL2 co-expression." (PMID 37176074, 2023). "However, further clinical trials indicated that Carlumab did not block the CCL-2/C–C chemokine receptor 2 (CCR-2) axis, nor did it show anti-tumor activity in metastatic castration-resistant prostate cancer." (PMID 36260158, 2023). "Similarly, stimulation of mBMMs adhered to complex-tumor-derived CDMs with and without TNC and with CCL2 did not induce TNFα production regardless of the TNC content of the matrix." (PMID 37176074, 2023). "In summary, the impact of vitamin D3 supplementation or calcitriol administration on blood flow or CAFs and lung NFs is not visible in less invasive tumor models, such as 67NR, despite induced changes in plasma and/or tumor tissue concentrations of OPN, CCL2, TGF-β, VEGF, and FGF23." (PMID 36230508, 2022). "Notably, nitrogen-derived post-translational modifications (PTMs) of CCL2 drastically affect tumour homing of CD8+ T lymphocytes, while in contrast, nitrated/nitrosylated CCL2 does not lose the ability to engage MDSCs in the TME." (PMID 34685679, 2021). "Furthermore, in keeping with the effect of EZH2 inhibition in tumor cells, Mo-TAMs from EPZ-6438-treated MCS showed a consistent enhanced expression of monocyte chemoattractants CCL2 and VEGF but not Th1-recruiting chemokines (CXCL9, CXCL10, CXCL11)." (PMID 33922336, 2021). "The quantitative PCR results were consistent with the transcriptome results, showing that the expression of CCL2, CCL3, CCL5, and CXCL9, but not CCL17 or CCL22, was markedly higher in 1.5 mg/kg AAGL-treated tumor-bearing mouse livers than in those of control mice." (PMID 33710817, 2021). "Blocking of CCL2 may control TAM accumulation in primary tumors, impacting blood vessel leakiness and circulating tumor cells, without directly preventing the primary tumor growth." (PMID 34572013, 2021). "Monocyte chemoattractant protein 1 (MCP-1, also known as CCL2) and other chemokines as CXCL1, CXCL3, CXCL5, and CCL8 can act as mediators of angiogenesis and tumor progression, while those without the ELR motif (CXCL4, CXCL9, CXCL10, CXCL11, and CXCL14) have been shown to inhibit angiogenesis." (PMID 32422889, 2020). "In the simultaneous low-grade lesion, instead, the lack of contrast enhancement suggests the presence of an intact BBB, which, coupled to low or absent presence of CCL2, may explain the absence of suppressive BMDM in the tumor microenvironment." (PMID 32642721, 2020).
tumor (continued). "Cytokine profiling of conditioned media from the co-culture of 3-D MVNs with tumor spheroids revealed a cooperative production of multiple chemo-attractants downstream of STING such as CXCL10, CCL5, and CCL2, which was surprisingly independent of cancer cell STING." (PMID 33013881, 2020). "Hence, both Ccl2 and Il13 are sufficient to elicit MYC-HCC to metastasize, even if Twist1 is not expressed in the tumor cells." (PMID 31933479, 2020). "Although we have not accessed the concentration of CCL2 in SW treated animals, this result corroborates the observation that SW may decrease CCL2 secretion by TAM, reducing the recruitment of cells to the tumor microenvironment." (PMID 30840689, 2019). "Interestingly, reactive nitrogen species produced by MDSCs induce post-translational modifications in CCL2 that decrease its affinity to CCR2 and its chemoattractant effects on CD8+ T cells, but not myeloid cells, into the tumor." (PMID 30619850, 2018). "None of them showed CCL2 or CCR2 could promote NPC cell growth rate, tumor formation in contact-independent cell growth or anchorage-independent cell growth." (PMID 26701209, 2016). "We hypothesize that our inability to detect a reduction in tumor CCL2 content in vivo is due to the lack of paired human or mouse tumor tissue samples before and after EPA treatment combined with tumor heterogeneity of CCL2 expression." (PMID 27058904, 2016). "Whilst depletion of CCL2 does not affect primary tumour growth, it is believed that monocytes facilitate metastatic seeding by vascular endothelial growth factor (VEFG)-A-mediated angiogenesis and that this occurs in a CCL2-dependent manner." (PMID 25990313, 2015). "The absence of CD14-positive cells within the tumour epithelium in ACP is unexpected as the β-catenin-accumulating epithelial whorls (cell clusters) express a variety of chemo-attractant cytokines (e.g., members of the CCL and CXCL family of chemokines including CCL2, CXCL1, CXCL3, CXCL11)." (PMID 39127699, 2024). "Furthermore, ZNF281 in CAFs upregulated CCL2 and CCL5 rather than VEGFA expression, which stimulated angiogenesis and vascular permeability through P38 MAPK signaling in endothelial cells, consequently contributing to lung PMN formation in tumor metastasis." (PMID 36438499, 2022). "Since CCL2 secreted by tumors could not become a chemoattractant towards CCR2low CD8+ T cells, generation of the functional CCR2-expressed CAR-T cells were reported to better localize in the tumor microenvironment." (PMID 34386431, 2021). "Interestingly, these tumour cells secrete CCL2, yet failed to induce maximal immune cell recruitment to the tumour site, implying that TME-derived CCL2 may play a greater role in trafficking of these immunosuppressive cells." (PMID 33803414, 2021). "However, it has also been found that CCL2 blockade does not inhibit the recruitment of TAMs, but tilts the polarization of TAMs toward M1, showing a stronger anti-tumor phenotype, and activating CD8+ T cells in the tumor to destroy the tumor cell." (PMID 33224886, 2020). "The phenomenon that PGE2 potentiates the production of CCL2 and simultaneously reduces CXCL8 production by GM-CSF/IL-6 M-MDSC, could explain the observation that M-MDSC accumulate preferentially in PGE2-rich tumor site, rather than PMN-MDSC, although this hypothesis needs to be tested independently." (PMID 30936876, 2019). "Interestingly, ASPP2 KD, but not overexpression, increased the expression of CCL2, CCL5, and TNF-α and enhanced their secretion, which may promote macrophage recruitment to tumor tissues and support multiple aspects of tumor progression." (PMID 30389910, 2018). "We did not measure the CCL2 levels in the serum or lung after implantation of the TβR2WT PyMT into the MFP as compared to normal lung or lung after tail vein injection of PyMT-TβR2KO alone, so we cannot definitely equate the suppression of tumor outgrowth in the lungs to elevations in CCL2." (PMID 28143493, 2017).
tumor (continued). "The role of Twist1-induced CCL2 in angiogenesis has been demonstrated, which raises the possibility that FOXQ1 may induce angiogenesis in CRC by inducing Twist1; however, a role for FOXQ1 in inducing tumor angiogenesis and TME modification in CRC has not been evaluated." (PMID 33330033, 2020). "Interestingly, whether upregulating or downregulating CCL2/CCR2, tumorigenesis was not be influenced in two independent cell-line pairs, arguing against the possibility that the observed increment or reduction in metastasis are the result of tumor growth rate." (PMID 26701209, 2016).
infection (1,938 papers, 2004 to 2026). The state of being infected such as from the introduction of a foreign agent such as serum, vaccine, antigenic substance or organism. "These analyses highlighted a conserved response to infection associated with chemokines (Cxcl10, Ccl2) and cytokines (interferon signaling)." (PMID 40444956, 2025). "Infection of microglia was associated with a sharp increase in CCL2 and CXCL10 chemokine gene expression and the activation of many type I interferon stimulated genes (MX1, ISG15, ISG20, IFI27, IFITM3 and others)." (PMID 38737767, 2024). "Beta P20 infection was associated with greater inflammatory cytokine production (CCL2, CXCL1, IL-6) than P0 (p < 0.005, p = 0.051, p < 0.05, respectively)." (PMID 38365933, 2024). "The M2 infection module revealed Chil3, Il4, Cx3cr1, Emr1 and Ccl2 as hubs, while module M6, associated with vaccination, disclosed Prf1, Klrc1, IFN-γ, Ncr1 and Tbx21 as hub proteins." (PMID 39563428, 2024). "To elucidate the role of astrocyte-derived CCL2 during infection, we generated mice in which astrocytes were specifically deficient in CCL2 production." (PMID 38206985, 2024). "Human complete CCR2 deficiency is a genetic etiology of PAP, polycystic lung disease, and recurrent infections caused by impaired CCL2-dependent monocyte migration to the lungs and infected tissues." (PMID 38157855, 2024). "Gamma variant also showed sustained elevated CXCL10 and CCL2 chemokines compared to Ancestral infection." (PMID 37507719, 2023). "The association between the concentration of CCL2 and the severity of infection also indicates classical monocyte activation in severe cases of canine babesiosis." (PMID 36839438, 2023). "Infection with NTHi is also associated with transcriptional upregulation of cytokines CCL2 (MCP1), TNF, IL-1β, IL-6, CXCL8 and alarmins (TSLP, IL-33 and IL-25)." (PMID 37180449, 2023). "Infection with all variants induced elevated pro-inflammatory chemokine expression such as CCL2 and CXCL10 at 2 dpi but elevated expression was sustained longer in Alpha- and Gamma-infected tissues as observed at 5 dpi compared to Ancestral." (PMID 37507719, 2023). "The reduced numbers of macrophages were associated with a significant reduction of CCL2 levels during infection and higher bacteria counts in the MasR–/– mice in comparison with WT." (PMID 34874920, 2022). "In Sub AD cells, SARS-CoV-2 did not alter cytokine expression except for a modest increase in IL1B and CCL2—the latter only observed after infection with the CoV-2(P.1) variant." (PMID 36175400, 2022). "Ccl2 (C-C motif chemokine ligand 2) encodes CCL2 (or MCP-1), which can recruit monocytes, and dendritic cells to inflammatory sites in the status of either tissue injury or infection." (PMID 34059066, 2021). "The increase in CCL2 indicates that the worms have already migrated to the brain in the early stage of infection and causes neuropathic pain." (PMID 33917604, 2021). "Other transcripts encoding pro-inflammatory genes identified as up-regulated in response to sublethal PVM infection and down-regulated in response to L. plantarum include those encoding Ccl2, Ccl8, Cxcl9, Cxcl10, and resistin-like molecule alpha (Retnla)." (PMID 34959580, 2021). "Tip-DCs derived from Ly6Chi monocytes contribute to innate defense against L. monocytogenes; hence, infection is worse in mice deficient in CCL2 and CCL7 or in Ccr2-/- mice due to an increased bacterial burden." (PMID 33829283, 2021). "Strikingly, suppression of constitutive CCL2 was observed during MVA-infection, especially in TNF-deficient cells." (PMID 34711816, 2021). "We found that both MLE-12 cells and polarized mouse tracheal epithelial cells (mTECs) were susceptible to infection with Influenza A and released proinflammatory cytokines, including CCL2, CCL5, CXCL1, and CXCL10, in response to replicating virus." (PMID 33374950, 2020).
infection (continued). "Following infection with the 2×scr virus, we observed the most striking differences for Ccl2 and Ccl7, two macrophage-associated chemokines, with ~10-100-fold increase in the testes on day 3 post infection over testes obtained from mock-inoculated mice." (PMID 32614902, 2020). "The splenic infection of L. donovani causes a constitutive expression of chemokine ligand 2 (CCL2) or monocyte chemoattractant protein 1 (MCP-1), which triggers IL-4 secretion from Th2 cells that activates the MΦs in alternative manner." (PMID 31024534, 2019). "IL-21 also induced expression of the CCL2 gene, which encodes MCP1, a chemokine that recruits additional innate cells to sites of infection." (PMID 30969166, 2019). "Infection of mice with STm caused an upregulation of Ccl2, Tnfa, Il17a, and Ifng at all-time points investigated." (PMID 30487793, 2018). "The transcript encoding MCP1/CCL2, a key chemokine for recruiting monocytes and macrophages, was increased up to 1,000-fold following infection of monocytes with C. pneumoniae." (PMID 30356749, 2018). "CCL2−/− mice showed less weight loss, a lower mortality rate, improved lung edema, and ameliorated histopathological changes post-infection." (PMID 28421067, 2017). "Together, these findings highlighted the role of STING and CCL2 as early host susceptibility factors that work by enabling recruitment of peripheral monocytes to sites of infection." (PMID 28844797, 2017). "We also established that in CCR2 deficient mice IFN-γ and CCL2 induction by infection with P. chabaudi was similar to infected wild type mice whereas CCL7 was constitutively deregulated." (PMID 23762028, 2013). "ILK-ko mice exhibited reduced weight loss at 15 days post-infection (p < 0.01) and demonstrated reduced histological inflammatory scores (p < 0.01), reduced CCL2 and pro-inflammatory cytokines." (PMID 24024606, 2013). "CCL2-deficient mice exhibit reduced recruitment of macrophages to the colonic mucosa and are also unable to expel T. muris during a primary infection." (PMID 19968992, 2010). "This suggests the initial blood sampling triggered CCL2 production, which concurs with the known crucial role of CCL2 in the recruitment of monocytes and other immune cells to sites of inflammation caused by tissue injury or infection." (PMID 40760251, 2025). "Although the expression of Ccl2 increased in WT and Tac1−/− mice infected with C. rodentium, this was not statistically significant across genotypes suggesting that select chemokines are modulated by infection and deficiency in Tac1." (PMID 40501768, 2025). "However, an intriguing study showed that CCR2 deficiency results in better clinical outcomes in mice upon JEV infection, while CCL2 deficiency renders mice highly susceptible to infection." (PMID 38997413, 2024). "Although we have associated miR-126 with tsc1 and the cxcl12a/ccl2/ccr2 axis by combinatorial gene depletion studies, miR-126 has been documented to be involved in additional pathways that may impact the outcome of infection." (PMID 38307625, 2024). "Moreover, human cardiomyocytes exposed to SARS-CoV-2 increased CCL2 secretion, recruiting monocytes to the site of infection, and the monocyte recruitment-associated protein CCL-2/MCP-1 was linked to fibrosis in a cohort study." (PMID 39444690, 2024). "Infected macrophages serve as a possible reservoir for CHIKV and may contribute to the persistent inflammation driven by secretion of cytokines (e.g., IL-6, CCL2) and joint pain associated with infection." (PMID 36078125, 2022). "Moreover, an increase in the concentration of CCL2, G-CSF, GM-CSF, and IL-6 was previously reported to be associated with local neutrophil recruitment upon infection." (PMID 35401577, 2022). "Finally, polymorphisms in the CCL2 gene have been shown to influence the outcomes of infection with Mycobacterium tuberculosis." (PMID 35880881, 2022).
infection (continued). "Moreover, we observed that serum CCL2 levels peak at 3 h after infection and this was temporally associated with high levels of CCL2 in the brain and hippocampus." (PMID 35615063, 2022). "To investigate sources of CCR2 ligands that might underlie recruitment of pre-cDCs to infection foci, we used PrimeFlow analysis to quantify Ccl2 transcripts by flow cytometry." (PMID 34739343, 2021). "As infection progressed, we detected a robust upregulation of genes encoding cytokines and chemokines (CCL2, CCL3, IL1B, CXCR1, IL1RN) as well as granulocyte associated transcripts (TLRs 1-4, SPI1, S100A8, S100A9, CD177), which correlated with the higher numbers of granulocytes 5 DPI." (PMID 28852031, 2017). "However, CCL2 deficiency or CCL2 antibody treatment enhances damage and impedes repair of the alveolar epithelium after infection with a sublethal dose of influenza A virus or mouse-adapted human influenza virus." (PMID 28421067, 2017). "Furthermore, our findings suggest that STING and CCL2 are host susceptibility factors that act at the very first steps of infection." (PMID 28844797, 2017). "Other studies have also associated CCL2 upregulation with poorer outcomes of infection." (PMID 27825367, 2016). "Interestingly, high expression levels of the monocyte chemoattractant protein MCP-1 (CCL2) have been associated with defects in the recruitment of monocytes to sites of infection and with subsequent increases in host susceptibility to Lm." (PMID 26381144, 2015). "These exciting results clearly indicate that the response of ‘arthritic’ osteoblasts to RRV infection differs from normal osteoblasts; they are more susceptible to infection possibly through delayed type I IFNs response and produce higher levels of IL-6, IL-1β, CCL2 and TNF-α." (PMID 25407789, 2014). "CCL-2, which recruits monocytes, memory T cells, and dendritic cells to inflammation sites produced by either tissue injury or infection, is implicated in the pathogenesis of several diseases characterized by monocytic infiltrates, including neuroinflammatory processes." (PMID 25126550, 2014). "Inducing an increase in CCL2 in blood could represent a mechanism the virus uses to attract susceptible cells to areas of infection and increase viral dissemination." (PMID 24083897, 2013). "The results suggest that in pigs infected with the virulent isolates, elevation in levels of CCL2 may be a mechanism by which monocytes are recruited to circulation increasing the pool of cells susceptible to infection." (PMID 24083897, 2013). "Excessive levels of CCL-2 may however lead to increase risk of infection and disease progression by virtue of its ability to activate the Th2 circuit." (PMID 21991356, 2011). "In the ferret model with 27% mortality based on the >20% weight loss following infection with A/California/07/2009 pandemic influenza virus, sequential lung sampling documented decreased gene expression of CCL2, CXCL10, TNFA and IL1B on day 7 when animals show highest weight loss." (PMID 20957032, 2010). "As a consequence, raised CCL2 in itself may be associated with clinical disease severity and dissemination of infection in the host." (PMID 20041183, 2009). "To illustrate, disease exacerbation in L. braziliensis patients has been associated with elevated CCL2 levels, suggesting that this chemokine may contribute to disease worsening by recruiting fresh monocytes to the infection site or influencing downstream events in macrophages and other cells." (PMID 41259559, 2025). "To determine if this antimicrobial pathway was affected in mice deficient in astrocyte-derived CCL2, we measured iNOS+ myeloid cells using flow cytometry and detected a decrease in the number of these cells in the knockout compared to the control mice during infection." (PMID 38206985, 2024).